ERCC1 (ERCC excision repair 1, endonuclease non-catalytic subunit)
Diseases named in the same sentence as ERCC1 in open-access papers (continued):
Sharing a sentence is not in itself a finding about the gene and the disease.
ovarian carcinoma (74 papers, 2005 to 2024). A malignant neoplasm originating from the surface ovarian epithelium. "ERCC1 rs11615 was associated with an increased risk of grade 3-4 anemia in 290 ovarian cancer patients (OR = 1.61; 95% CI: 1.04–2.50; p = 0.031) and 437 NSCLC patients (OR = 2.230; 95% CI: 1.041–4.775; p = 0.039)." (PMID 39234108, 2024). "In in vitro human ovarian carcinoma, CsA treatment decreases the expression of ERCC1, a key factor in DNA repair through NER that is linked to cisplatin resistance." (PMID 36230472, 2022). "In ovarian cancer, resistance to platinum-based chemotherapy has been associated with high levels of ERCC1 mRNA." (PMID 36551731, 2022). "E-X PPI2 inhibited the NER activity in melanoma cells, showed marginal sensitivity to cisplatin treatment but caused significant reduction in the level of ERCC1-XPF heterodimer levels in ovarian cancer cells." (PMID 35463312, 2022). "In conclusion, the ERCC1 rs11615 polymorphism is associated with the sensitivity of platinum-based combination chemotherapy in patients with ovarian cancer, especially in the Asian population." (PMID 34148553, 2021). "For example, increased expression of the NER genes ERCC1 and ERCC4/XPF is associated with cisplatin resistance in ovarian cancer cells, while knockdown of ERCC1 enhanced cellular sensitivity to cisplatin." (PMID 34645978, 2021). "There are also plenty of studies on the relationship between ERCC1 gene polymorphism and platinum chemotherapy sensitivity in patients with ovarian cancer." (PMID 34148553, 2021). "In consideration of the correlation between ERCC1 rs11615 polymorphism and platinum chemosensitivity of ovarian cancer in the Asian population, a targeted sensitivity analysis in the Asian population was conducted." (PMID 34148553, 2021). "This has critical clinical significance, which not only points out a key direction for further research, but also provides a crucial basis for individualized treatment of ovarian cancer patients according to ERCC1 gene polymorphism in the future." (PMID 34148553, 2021). "Instead, we found ERCC1 rs11615 G>A polymorphism was associated with significantly reduced risk for ovarian cancer." (PMID 29669843, 2018). "ERCC1 rs3212986 were related with the increased risk of ovarian cancer under recessive model (adjusted OR = 2.40, 95% CI = 1.30–4.44, P=0.005)." (PMID 29669843, 2018). "As a result, we found that both variant genotypes of XPC rs2228001 A>C and ERCC2 rs238406 G>T as well as ERCC1 rs3212986 C>A had a significant association with the increased risk of ovarian cancer under dominant and recessive genetic model respectively." (PMID 29669843, 2018). "In this study, we performed a meta-analysis of the published literature to assess the association between the ERCC1 protein expression and the response to platinum-based chemotherapy in patients with ovarian cancer." (PMID 28623887, 2017). "A total of 15 research articles reporting the association of human ERCC1 gene polymorphisms and platinum-based chemotherapy effectiveness in ovarian cancer were identified." (PMID 28623887, 2017). "To map the 5’ end of this larger ERCC1 variant, we performed 5’ RACE assay on the ovarian cancer cells using the ERCC1 specific reverse primers from upstream of the normal transcriptional start site." (PMID 29156754, 2017). "In other tumors treated with platinum-based chemotherapy, such as ovarian cancer, malignant mesothelioma, or advanced squamous cell carcinoma of the head and neck, association of the ERCC1 8092Ala allele with poor survival has been consistently reported." (PMID 25025378, 2014). "Over-expression of XPA and ERCC1 mRNA has been associated with cisplatin resistance in ovarian cancer." (PMID 21696631, 2011). "In clinical studies high ERCC1 expression was associated with resistance to platinum containing therapy in various human cancers including colorectal cancer, ovarian cancer or NSCLC." (PMID 20846399, 2010).
ovarian carcinoma (continued). "Ovarian cancer identified in this study was closely related to ERCC1 gene polymorphisms." (PMID 37141338, 2023). "High expression of ERCC1 has also been linked to chemoresistance in ovarian cancer patients." (PMID 36551731, 2022). "The results showed that the rs11615 polymorphism of the ERCC1 gene was strongly associated with ovarian cancer patients in the Asian population, and the differences were statistically important in allele, dominant, recessive, homozygous, and heterozygous genetic models." (PMID 34148553, 2021). "Consequently, it can be concluded that the rs11615 polymorphism of the ERCC1 gene is associated with ovarian cancer patients in the Asian population." (PMID 34148553, 2021). "β-Elemene is reported to enhance the sensitivity of resistant ovarian cancer cells to cisplatin by downregulating excision repair cross-complementation group-1 (ERCC-1) and X-linked inhibitor of apoptotic protein (XIAP) and inactivating c-Jun NH2-terminal kinase (JNK)." (PMID 34641334, 2021). "Pubmed, Web of Science, EMBASE, Cochrane Library, China National Knowledge Infrastructure (CNKI), and China Wanfang databases were comprehensively searched up to September 2020, to identify the relationship between ERCC1 rs11615 polymorphism and chemosensitivity of ovarian cancer." (PMID 34148553, 2021). "Besides, compared with the carriers of ERCC1 rs3212986 AC/CC genotype, the carriers of AA genotype had a significant association with the increased risk of ovarian cancer at an adjusted OR of 2.40 (95% CI = 1.30–4.44, P=0.005)." (PMID 29669843, 2018). "Besides, a previous study in cell lines got coincident results that ERCC1 levels in human ovarian cancer cell (MCAS) with T allele of SNP rs11615 reduced almost 60% of that in human ovarian cancer cell (A2781/CP70) with wild-type ERCC1 sequence." (PMID 28743890, 2017). "At least for ERCC1, detection of a particular splice variant might be important for the evaluation of platinum resistance, as has been reported for ovarian cancer cells." (PMID 22866924, 2012). "Our data suggest that HOXB9 overexpression may cause chemoresistance in ovarian cancer cells by differential induction of ERCC-1, MRP-2, and XIAP depending on the strength of HOXB9 expression through inhibition of the mitochondrial pathway of apoptosis, including Bax/Bcl-2." (PMID 36674764, 2023). "Therefore, we systematically reviewed the related literature in this study, applying meta-analysis to conduct a comprehensive analysis upon the relationship between the ERCC1 rs11615 polymorphism and the chemosensitivity of platinum drugs in patients with ovarian cancer." (PMID 34148553, 2021). "With respect to DNA repair genes, low ERCC1 (excision repair cross-complementing rodent repair deficiency, complementation group −1) expression has been associated with a better outcome upon platinum compounds initially in patients with ovarian cancer and later in patients with NSCLC." (PMID 22866924, 2012). "In ERCC1 rs11615, the CT and CC genotypes predicted a better response to platinum in ovarian cancers than the TT genotypes." (PMID 37141338, 2023). "The expression of ERCC1 is significantly elevated in ovarian cancer tissues and can serve as a critical indicator to judge the severity of ovarian cancer." (PMID 37420272, 2023). "Subsequently, subgroup analysis was performed according to cancer type, which showed that the ERCC1 rs11615 CT+TT genotype in ovarian cancer was related to a better platinum response." (PMID 37141338, 2023). "The wet lab analysis of PRKCG SNP rs1331232028, like many other SNPs in multiple genes, including ERCC1, XPC, PIK3CA, ERBB2 and ERCC2, can be linked to ovarian cancer susceptibility." (PMID 36672978, 2023). "A low expression of ERCC1 reflects a better chemosensitivity in ovarian cancer patients than a high expression." (PMID 37420272, 2023).
ovarian carcinoma (continued). "Studies have shown that silencing ERCC1 reverses resistance to cisplatin in gastric and ovarian cancers." (PMID 35204785, 2022). "PGPIPN significantly decreased MDR1 and ERCC1 proteins of drug-resistant ovarian cancer cell lines and human primary ovarian cancer cell in a dose-dependent manner (P<0.05 or P<0.01)." (PMID 34539881, 2021). "PGPIPN significantly decreased MDR1 and ERCC1 of drug-resistant ovarian cancer cell lines and human primary ovarian cancer cell in a dose-dependent manner." (PMID 34539881, 2021). "In cisplatin-resistant ovarian cancer cells, β-elemene inhibits cisplatin-induced expression of ERCC-1, a marker gene for the repair of cisplatin-induced DNA damage in the nucleotide excision repair pathway." (PMID 34641334, 2021). "In recent years, there have been many studies on the direct relationship between ERCC1 and cisplatin resistance in ovarian cancer." (PMID 34539881, 2021). "Elevated ERCC1 is also suggested to contribute to chemoresistance in ovarian cancer, although the number of OCCC in the study was very small." (PMID 34737943, 2021). "We conducted the study to investigate the association between polymorphisms of ERCC1, XRCC1 and GSTP1, which responsible for platinum’s metabolisms in Thai epithelial ovarian cancer patients." (PMID 32711417, 2020). "ERCC1/XPF complexes were detected in untreated A2780 ovarian cancer cells and a significant increase in their number was observed at 24 h and 48 h after DDP treatment with 10 μM (p = 0.03 and p = 0.02, respectively)." (PMID 32847049, 2020). "As in previous reported, ERCC1, XRCC1 and GSTP1 polymorphisms had impacts on treatment responses of platinum based chemotherapy among epithelial ovarian cancer patents." (PMID 32711417, 2020). "Some important associations of ERCC1, XRCC1 and GSTP1 polymorphisms of clinical outcomes and adverse events in Thai epithelial ovarian cancer patients were noticed." (PMID 32711417, 2020). "During the onset of carcinogenesis, shifted splicing of DNA repair genes has previously been documented in several cancer studies, such as BRCA1 and FANCM in breast cancer and ERCC1 in ovarian cancer." (PMID 31636653, 2019). "Among the NER proteins, ERCC1 is the most studied as a possible predictive biomarker of platinum response in different tumor types, including ovarian carcinoma." (PMID 30669514, 2019). "We have preliminary data showing that in ovarian cancer patient xenografts made resistant in vivo to cisplatin, a higher level of ERCC1/XPF complex detected by PLA was found compared to platinum-sensitive xenografts." (PMID 30669514, 2019). "On the contrary, ERCC1 rs11615 G>A and XPC rs2228000 C>T polymorphisms were associated with significantly reduced risk for ovarian cancer under dominant model." (PMID 29669843, 2018). "E-X PPI2 significantly reduced ERCC1-XPF heterodimer levels in ovarian cancer cells, blocked NER activity (IC50 = 20 μM) and enhanced melanoma cell sensitivity to cisplatin." (PMID 30208165, 2018). "We, therefore investigated the larger ERCC1 transcript in human ovarian cancer cell A2780 by RT-PCR." (PMID 29156754, 2017). "It sensitized ovarian carcinoma cells to cisplatin treatment by down-regulating excision repair cross-complementation group-1 (ERCC-1) and XIAP through JNK pathway." (PMID 28337141, 2017). "A 42-bp spliced sequence in the 5’-UTR of ERCC1 gene has been shown to influence the response of ovarian cancer to cisplatin therapy." (PMID 29156754, 2017). "In this study, we identified a novel ERCC1 transcript in ovarian cancer cells, originating from upstream of normal ERCC1 transcriptional start site and investigate its role in platinum-based chemotherapy." (PMID 29156754, 2017).
ovarian carcinoma (continued). "Some suggest prognostic value of ERCC1 in ovarian cancer, whereas others express limited clinical significance of the gene in primary ovarian cancer patients." (PMID 29156754, 2017). "We now explored in more detail how additional assessment of ERCC1 influences the overall detection rate of CTCs in 65 paired pre-operative and post-chemotherapeutic blood samples from ovarian cancer patients." (PMID 28388557, 2017). "ERCC1 mRNA increased by 6-fold in human ovarian cancer cells exposed to cisplatin, possibly due to increased expression of transactivating factors and c-Jun phosphorylation." (PMID 28977987, 2017). "Subsequently, we were interested in how auxiliary assessment of ERCC1 influences the overall detection rate of CTCs in ovarian cancer." (PMID 28388557, 2017). "This indicated that the novel larger ERCC1 transcript originating upstream of ERCC1 existed in human ovarian cancer cells." (PMID 29156754, 2017). "The larger ERCC1 transcript and total ERCC1 mRNA expression levels (normalized to β-actin as internal control) in ovarian cancer tissues of these patients were evaluated by real-time PCR." (PMID 29156754, 2017). "We previously have demonstrated that ERCC1 extends clinical information of CTCs as a prognostic biomarker to the prediction of platinum-resistance at primary diagnosis of ovarian cancer." (PMID 28388557, 2017). "Higher expression level of ERCC1 reduced the sensitivity of ovarian cancer and other cancers to cisplatin." (PMID 29156754, 2017). "All together, cisplatin treatment induced a time- and dose- dependent larger ERCC1 increase in ovarian cancer cells." (PMID 29156754, 2017). "We recently showed that the presence of ERCC1+CTCs is an independent predictive biomarker for platinum-resistance and poor prognosis of ovarian cancer." (PMID 28388557, 2017). "We further showed that the presence of ERCC1+CTCs after chemotherapy correlated with post-therapeutic outcome of ovarian cancer and, particularly, dynamics of ERCC1+CTCs mirrored response to platinum-based chemotherapy." (PMID 28388557, 2017). "In the present study we demonstrate that the additional assessment of ERCC1-transcripts enhanced overall CTC detection rate in ovarian cancer patients." (PMID 28388557, 2017). "The expression of larger ERCC1 transcript has stronger influence on drug sensitivity and behavior of ovarian cancer cells in response to cisplatin." (PMID 29156754, 2017). "Cisplatin treatment induced approximately 5.3-fold and 2.6-fold increase in larger ERCC1 mRNA expression in ovarian cancer cells PEO14 and A2780 respectively." (PMID 29156754, 2017). "ERCC1-expression has been extensively studied in primary tumor tissue of several cancer entities, including ovarian cancer, and has been proposed as a potential predictor for response to platinum-based chemotherapy." (PMID 28388557, 2017). "It suggested that cisplatin selectively induced the expression of the larger ERCC1 transcript in ovarian cancer cells." (PMID 29156754, 2017). "Similar to the transcriptional data, our data indicated that cisplatin treatment induced ERCC1 protein expression in ovarian cancer cells." (PMID 29156754, 2017). "Studies have indicated that ERCC1 mRNA and protein expressions can be used as biomarkers for patients’ outcomes in ovarian cancer." (PMID 28623887, 2017). "More importantly, the larger ERCC1 transcript enhanced ovarian cancer cells resistance to cisplatin treatment." (PMID 29156754, 2017). "The expression of this larger ERCC1 transcript dramatically increased following cisplatin treatment in ovarian cancer cells and was regulated by the MAPK pathway." (PMID 29156754, 2017). "The expression of DNA repair genes such as excision repair cross-complementation group-1 (ERCC-1) and xeroderma pigmentosum complementation group A (XPA) is reported to be strongly associated with a poor prognosis in ovarian carcinoma and other tumors." (PMID 23817665, 2013).
ovarian carcinoma (continued). "In the cisplatin-resistant ovarian carcinoma cells, β-elemene abrogated cisplatin-induced expression of excision repair cross-complementation group-1 (ERCC-1), a marker gene in the nucleotide excision repair pathway that repairs cisplatin-caused DNA damage." (PMID 23817665, 2013). "For example, one RBM38-regulated splicing event, activation of excision repair cross complementation group-1 (ERCC1) exon 8, occurs in ovarian cancer cells and has been linked to cisplatin-resistance." (PMID 24250749, 2013). "For instance, expression of ERCC1 has been shown to increase the resistance to platinum treatment in patients with ovarian cancer." (PMID 20470393, 2010). "ERCC1 has a high homology with the yeast excision repair protein RAD10, is reduced in testis neoplasms and ovarian cancer cell lines." (PMID 16893473, 2006). "Up-regulation of ERCC1 expression was found in all 10 ovarian cancer samples exposed to topotecan (p < 0.002, Wilcoxon), and in all 7 colorectal specimens treated with irinotecan, although in this group the increase was modest (p = 0.016, Wilcoxon)." (PMID 16026610, 2005). "Furthermore, a correlation has been identified by researchers between chemo-resistance and a distinct set of genes (MRP1–10, MDR1, RRM1/2, ERCC1) that have potential as therapeutic targets for patients with chemo-resistant ovarian cancer." (PMID 39492906, 2024). "Therefore, we conclude that naringin is able to eliminate cisplatin resistance in ovarian cancer by modulating the p38 signaling pathway and decreasing ERCC1 expression in cells." (PMID 38947385, 2024). "Moreover, decreased expression of ERCC1 is strong related to improved progression free survival in patients with epithelial ovarian cancers." (PMID 37420272, 2023). "The overexpression of ERCC1-XPF has been linked with poor responses to chemotherapy in various cancers including NSCLC, squamous cell carcinoma, ovarian cancer and melanoma while low ERCC1-XPF expression observed in testicular cancer has extended overall survival of cancer patients." (PMID 35463312, 2022). "The ERCC1 rs11615 polymorphism is associated with chemosensitivity in patients with ovarian cancer, especially in the Asian population, but not in the Caucasian population." (PMID 34148553, 2021). "At present, the conclusions upon the rs11615 polymorphism of the ERCC1 gene and the chemosensitivity of platinum drugs in ovarian cancer are not consistent." (PMID 34148553, 2021). "At present, our study found that there is a correlation between ERCC1 rs11615 polymorphism and chemotherapy sensitivity of ovarian cancer in the Asian population, but not in the Caucasian population." (PMID 34148553, 2021). "Similarly, PGPIPN significantly reduced MDR1 and ERCC1 mRNAs of drug-resistant ovarian cancer cell lines and human primary ovarian cancer cell in a dose-dependent manner." (PMID 34539881, 2021). "We have previously reported that both paclitaxel and cisplatin, standard chemotherapies used for the treatment of ovarian cancer patients, promotes an increase in the expression of the chemoresistant markers ERCC1 and TUBB3 and the CSC markers CD44, CD133, OCT4A and EpCAM in ovarian cancer cells." (PMID 33023532, 2020). "The association between genetic polymorphisms of ERCC1, XRCC1 and GSTP1 with progression free survival (PFS) and overall survival (OS) in patients with epithelial ovarian cancer in varies ethnicities such as American, European or Asian were reported in several studies." (PMID 32711417, 2020). "Genetic polymorphisms of ERCC1, and GSTP1 might be useful biomarkers for prediction of clinical benefit and toxicities of platinum-based chemotherapy in Thai epithelial ovarian cancer patients." (PMID 32711417, 2020). "In conclusion, our study indicated that the ERCC1, XPC and ERCC2 might correlate to ovarian cancer susceptibility." (PMID 29669843, 2018).